PTH (parathyroid hormone)
Diseases named in the same sentence as PTH in open-access papers (continued):
Sharing a sentence is not in itself a finding about the gene and the disease.
Hypercalcemia (continued). "Classically, the overproduction of PTH leads to hypercalcemia through increased calcium release from bones, increased calcium reabsorption in the kidneys, and increased calcium absorption from the intestines." (PMID 39040613, 2024). "Another consideration is represented by developing pancreatitis in PTH-independent hypercalcemia as prior mentioned in primary hyperparathyroidism-derivate hypercalcemia." (PMID 38928056, 2024). "As an allosteric activator of the calcium-sensing receptor, cinacalcet inhibits PTH release, as well as lowers serum calcium, making the drug ideal for patients with hyperparathyroidism and hypercalcemia." (PMID 38820324, 2024). "One patient with PTC experienced hypercalcemia due to ectopic PTH secretion by the tumor, and another one, PTHrP-mediated hypercalcemia and CSF-mediated massive leukocytosis." (PMID 38320311, 2024). "We described a woman with asymptomatic mild hypercalcaemia and ambiguous low-normal PTH, which made the initial classification of hypercalcaemia difficult." (PMID 38665259, 2024). "Both Gna11+/– and Gna11–/– mice demonstrated hypercalcemia and mildly raised parathyroid hormone levels, consistent with FHH." (PMID 38530370, 2024). "Compared to the no treatment group, recipients who were treated for hypercalcemic tHPT had higher PTH levels before KT (P = .002) and earlier onset of hypercalcemia post-KT (P < .001)." (PMID 38006197, 2024). "We present a complex case of a 79-year-old man who presented with severe hypercalcaemia arising from a parathyroid mass that produced excessively high levels of parathyroid hormone." (PMID 39087171, 2024). "Familial hypocalciuric hypercalcemia (FHH) is marked by mild to moderate hypercalcemia, normal-elevated serum PTH levels, and relative hypocalciuria." (PMID 38832006, 2024). "Subsequently, biallelic pathogenic variants in CYP24A1 were also discovered in adults with elevated vitamin D, suppressed parathyroid hormone (PTH), hypercalcemia, hypercalciuria, osteopenia, and recurrent calcium nephrolithiasis." (PMID 38765596, 2024). "The ectopic adenoma was excised successfully, resulting in the resolution of hypercalcemia (calcium level: 10.3 mg/dL) and normalization of PTH levels (PTH: 18 pg/mL) within one hour after surgery." (PMID 39371798, 2024). "Vitamin D toxicity is clinically characterized by prolonged, severe and parathyroid hormone (PTH)-independent hypercalcemia resulting from the increased intestinal absorption of calcium and mobilization of calcium from bone." (PMID 39337491, 2024). "KTRs with normalized PTH and recovered hypercalcemia had improved death-censored graft survival (p < 0.001) and overall patient survival (p < 0.001)." (PMID 39001249, 2024). "Early studies involving continuous PTH perfusion in humans returned deleterious systemic effects, with persistent hypertension and hypercalcemia being the most notable." (PMID 38785509, 2024). "The untreated group had milder diseases, as reflected by lower PTH levels at KT and later onset of hypercalcemia post-KT compared to the treated groups." (PMID 38006197, 2024). "The condition is typically characterised by inappropriately high PTH levels in the presence of high serum calcium levels, i.e., hypercalcaemia, due to the activation of osteoclasts increasing calcium levels via bone resorption." (PMID 38449925, 2024). "This disease is diagnosed in the setting of hypercalcemia with elevated or inappropriately normal PTH levels." (PMID 39963179, 2024). "Primary hyperparathyroidism (PHPT) is a disorder characterized by hypercalcemia due to an excessive secretion of parathyroid hormone (PTH)." (PMID 39845209, 2024). "In one patient, the long-term follow-up, 25 months after surgery, revealed a hypercalcemia (2.9 mmol/l) with a PTH value below the normal range." (PMID 39636417, 2024). "Hydration and calcitonin injections are the cornerstones of the treatment of PTH-rp-induced hypercalcemia during pregnancy." (PMID 39148641, 2024).
Hypercalcemia (continued). "Further biochemical profiling, including serum calcium, phosphorus, and parathyroid hormone (PTH) levels, showed elevated PTH and hypercalcemia, prompting consideration of primary hyperparathyroidism and the diagnosis of a brown tumor due to this condition." (PMID 38618395, 2024). "This case report aims to emphasize the importance of considering PTH-mediated hypercalcemia in the differential diagnosis of dysphagia, especially in patients presenting with hypercalcemia and without obvious causes of esophageal dysfunction." (PMID 39427404, 2024). "She developed worsening parathyroid hormone-mediated hypercalcemia that was refractory to escalating doses of cinacalcet and antiresorptive therapy." (PMID 39011405, 2024). "In our opinion, hydration and calcitonin are the cornerstones of treatment for PTH-rp-induced hypercalcemia." (PMID 39148641, 2024). "Hypercalcemia is a common complication of malignancy, often attributed to elevated PTH-related protein levels mimicking the effects of PTH and promoting bone resorption." (PMID 39544891, 2024). "PTH measurement is the key initial test for differentiating between PTH-dependent and PTH-independent hypercalcaemia." (PMID 38665259, 2024). "Clinical manifestations of HPT-JT include highly elevated serum PTH levels, hypercalcemia, parathyroid adenomas and fibro-osseous tumors in the mandible and maxilla, kidneys and uterus." (PMID 38281202, 2024). "Upon binding with the Vitamin D receptor, 1,25-dihydroxyvitamin D3(1,25D) directly inhibits parathyroid hormone gene transcription and antagonizes osteocalcin to prevent hypercalcemia." (PMID 39872315, 2024). "Primary hyperparathyroidism (PHPT), which is characterized by increased parathyroid hormone secretion, typically manifests as hypercalcemia and hypertension." (PMID 39213244, 2024). "When hypercalcemia coexists with elevated (or improperly normal) blood parathyroid hormone (PTH) concentrations, the diagnosis of PHP is made." (PMID 39201946, 2024). "Long-standing overproduction of parathyroid hormone (PTH) and hypercalcemia can lead to progressive damage to vital organs and even mortality." (PMID 39020280, 2024). "Plasma ionized calcium is the main regulator of PTH secretion, where in the setting of hypercalcemia, CaSR is stimulated, which inhibits PTH secretion on parathyroid chief cells." (PMID 38396761, 2024). "Serum parathyroid hormone (PTH) levels are evaluated if they are raised, and the diagnosis of hypercalcemia is made based on high or abnormally high PTH levels." (PMID 39201946, 2024). "The stabilization of her serum calcium levels also demonstrates its efficacy in addressing hypercalcemia, even when non-PTH mediated, another less commonly reported scenario." (PMID 39669861, 2024). "We describe a 73-year-old female (patient A) who presented with mild parathyroid hormone (PTH)-dependent hypercalcaemia and a history of osteoporosis." (PMID 38343604, 2024). "Primary hyperparathyroidism is an endocrine disorder of the parathyroid glands, generally due to a benign overgrowth of parathyroid tissue, in which there is hypercalcemia and inappropriately normal or elevated PTH and is commonly treated by surgery." (PMID 39408619, 2024). "Primary hyperparathyroidism (PHPT) is a disease characterized by hypercalcemia due to the excessive autonomous production of parathyroid hormone (PTH) from one or more of the parathyroid glands." (PMID 38910736, 2024). "The etiology of hypercalcemia can be separated into 2 major categories, parathyroid hormone (PTH)-dependent and PTH-independent." (PMID 39439809, 2024). "Laboratory results indicated hypercalcemia with serum calcium at 8.9 mg/dL and elevated PTH at 115.8 pg/mL." (PMID 39246902, 2024). "PTH-dependent hypercalcemia indicating persistent PHPT was excluded, since PTH concentrations were sufficiently suppressed." (PMID 39529981, 2024).
Hypercalcemia (continued). "Serum PTH level was 15.9 pg/mL (1.7 pmol/L) (normal reference range,15-65 pg/mL; 1.6-6.9 pmol/L), indicating PTH-independent hypercalcemia." (PMID 39439809, 2024). "This systemic disorder is characterized by excess parathyroid hormone (PTH) secretion and resultant hypercalcemia." (PMID 38975429, 2024). "Among the patients with increased PTH, all children had normal serum calcium concentrations, while 1 adult patient had hypercalcemia and 1 adult patient had hypocalcemia." (PMID 38226986, 2024). "The patient underwent a successful robotically assisted thymectomy, guided by intraoperative PTH monitoring, which resulted in the resolution of hypercalcemia and normalization of PTH levels." (PMID 39371798, 2024). "This case highlights not only the challenges of diagnosing and managing PTH-mediated hypercalcemia but also demonstrates the therapeutic benefits and risks associated with bisphosphonate treatment in complex cases involving advanced age and CKD." (PMID 39669861, 2024). "Patients suffering from hypercalcemia with low PTH are most likely to have hypercalcemia of malignancy (HCM); therefore, the level of PTHrP should be checked to confirm the presence of humoral hypercalcemia of malignancy." (PMID 38920679, 2024). "Current guideline of PC suggests that the possibility of PC should be considered in patients with greatly increased PTH level (>5-fold normal or >500 pg/mL) and severe hypercalcemia (>14 mg/dL)." (PMID 39777339, 2024). "Previous studies in HC-PHPT have not yet clarified which is the main responsible for the metabolic imbalance and the increase of cardiovascular morbidity and mortality between hypercalcemia and the rise of PTH serum levels." (PMID 39404961, 2024). "The whole notion about NHPT as an “entity” arose because of routinely PTH testing for conditions other than PHPT, in which instead hypercalcemia is the required characteristic before PTH is tested." (PMID 39963179, 2024). "Our case demonstrates the importance for a high suspicion for PJP in chronically immunosuppressed patients on rituximab presenting with PTH-independent hypercalcemia." (PMID 38658913, 2024). "Hypercalcemia and hypermagnesemia were independent from PTH and correlated with higher expression of claudin 16 and 19 in kidneys." (PMID 38386045, 2024). "Hyperparathyroidism is characterized by elevated blood parathyroid hormone levels that can result in hypercalcemia and other systemic consequences." (PMID 39834923, 2024). "This research has emphasized that suppressing CD36 or CD47 mitigates osteoclast formation, thereby inhibiting PTH-induced hypercalcemia in mouse models." (PMID 38167957, 2024). "The International Global Consensus Guidelines 2016 define vitamin D toxicity as hypercalcemia and serum 25(OH)D > 250 nmol/L (100 ng/mL), leading to hypercalciuria, suppressed PTH, and symptoms such as lethargy, abdominal pain, constipation, and polyuria." (PMID 38539363, 2024). "Parathyroid venous sampling (PVS) or selective venous sampling is an invasive method to localise abnormal parathyroid glands in the setting of PHPT (hypercalcemia and elevated PTH levels)." (PMID 39061231, 2024). "PHPT typically leads to hypercalcemia through excessive secretion of PTH, which increases calcium release from bones, absorption from the gut, and reabsorption by the kidneys​." (PMID 39669861, 2024). "Absence of Cyp24a1 in mice causes postnatal lethality in about 50% of neonates due to severe hypercalcemia (twice the wildtype [WT] value), which is accompanied by a marked elevation in calcitriol and undetectable PTH." (PMID 38577520, 2024). "PTH and PTH-RP were both undetectable, ruling out hyperparathyroidism and making hypercalcemia of malignancy unlikely." (PMID 38891746, 2024). "Considering parathyroid hormone (PTH) was at a low normal level despite severe hypercalcemia (PTH: 37 pg/ml), primary hyperparathyroidism was a consideration." (PMID 39350812, 2024).
Hypercalcemia (continued). "Parathyroid cancer usually presents with severe hypercalcaemia from significantly raised PTH levels compared with the typically more mild elevations seen with benign parathyroid disease." (PMID 39087171, 2024). "While the differential diagnosis for hypercalcemia is broad, it can often be narrowed by assessing parathyroid hormone (PTH) levels." (PMID 39539908, 2024). "It is characterized by normal or reduced levels of Calcitriol, very low or undetectable levels of PTH and hypercalcemia (rarely severe, more often mild), hypercalciuria, and hyperphosphatemia." (PMID 39629100, 2024). "When severe hypercalcemia and parathyroid hormone (PTH) levels are 3-10 times higher than normal, PC should be considered." (PMID 39777339, 2024). "Given the patient’s advanced age and CKD, her positive overall response to zoledronic acid offers valuable insights into the drug’s utility in PTH-mediated hypercalcemia and osteoporosis." (PMID 39669861, 2024). "Two months prior to her admission, she had been diagnosed with hypercalcemia (calcium level: 14 mg/dL; normal range: 8.6-10.2 mg/dL) and elevated PTH levels (PTH: 141 pg/mL; normal range: 15-65 pg/mL)." (PMID 39371798, 2024). "In this study, at the “F2” visit, there were 5 patients with PTH below the normal range and hypercalcemia and 16 with PTH below the normal range and calcium in the upper normal range (2.5–2.6 mmol/l)." (PMID 39636417, 2024). "A laboratory test revealed hypercalcaemia, hypercalciuria, and unsuppressed PTH levels (27 pg/mL, reference range, 15-65 pg/mL)." (PMID 38665259, 2024). "After transplantation, both groups showed an increase in patients with normal PTH and a decrease in patients with hypercalcemia." (PMID 39001249, 2024). "Hypercalcemia, suppressed PTH, hypophosphatemia, and impairment of renal phosphate conservation were demonstrated in laboratory data." (PMID 38504242, 2024). "The preoperative diagnosis of PC remains challenging; suspicion should arise in cases of severe hypercalcemia, elevated parathyroid hormone levels, and the presence of a mass on imaging or during surgery." (PMID 39768933, 2024). "Post-surgical follow-up examination revealed PTH-independent hypercalcemia consistent with a rebound hypercalcemia after cessation of long-term denosumab treatment." (PMID 39529981, 2024). "A subsequent comprehensive metabolic panel (CMP) conducted in February 2024 confirmed persistent hypercalcemia with a serum calcium level of 10.7 mg/dL and an intact PTH level of 116.5 pg/mL." (PMID 39246902, 2024). "In summary, our research has revealed that the occurrence of PTH-independent hypercalcemia, alongside other more commonly described rebound effects, can be a potential side effect following the discontinuation of denosumab." (PMID 39529981, 2024). "We present the case of a 27-year-old female who initially presented with nausea, vomiting, severe hypercalcemia, and elevated parathyroid hormone (PTH) levels." (PMID 39371798, 2024). "Interventions to lower the hypercalcemia were only temporarily effective, until a high serum parathyroid hormone (PTH) concentration of 1404 pg/mL was detected." (PMID 39020280, 2024). "This case illustrates the successful management of PTH-mediated hypercalcemia in an elderly patient with complex medical comorbidities." (PMID 39669861, 2024). "These included severe hypercalcaemia with acute kidney injury, a grossly elevated PTH level from a large parathyroid mass, acute orbital inflammation, and postoperative hungry bone syndrome." (PMID 39087171, 2024). "Diagnosis typically begins with identifying hypercalcemia on routine blood tests, followed by PTH level assessment." (PMID 39427404, 2024). "Both types of IIH present hypercalcemia, suppressed intact parathyroid hormone, hypercalciuria, and nephrocalcinosis." (PMID 38504242, 2024). "It is, therefore, essential to determine serum PTH levels to evaluate the impact of PHPT when persistent hypercalcemia is detected." (PMID 39020280, 2024).
Hypercalcemia (continued). "This case emphasizes the need for clinicians to consider rare but potentially serious causes of FUO, especially in patients with suggestive clinical findings such as hypercalcemia, neck masses, and severe parathyroid hormone elevations." (PMID 39822449, 2024). "For suspicion of parathyroid carcinoma recurrence, modern imaging methods should be considered for periodic surveillance or when biochemical recurrence occurs with increased PTH or hypercalcemia." (PMID 40729208, 2023). "Blood tests revealed severe hypercalcemia (3.39 mmol/L; reference value [RV] 2.1–2.55), hypophosphatemia (0.58 mmol/L, RV 0.87–1.45), and elevated parathyroid hormone (PTH) levels (4950 pmol/L, RV 95–618), consistent with PHPT." (PMID 36334246, 2023). "Vitamin D toxicity primarily present as elevated serum level of 25‐hydroxy vitamin D (i.e., >150 ng/mL), hypercalcemia, hyperphosphatemia, hypercalciuria, low parathyroid hormone, and high serum creatinine levels." (PMID 37415587, 2023). "Ultimately, these changes led to mild PTH-independent hypercalcemia, a renal pseudohyperparathyroidism phenotype likely caused by downstream activation of the PTH receptor signaling cascade by SIK gene deletion." (PMID 36862513, 2023). "Hypercalcemia, low plasma parathyroid hormone levels, and metabolic acidosis were present, while urinalysis revealed hematuria, proteinuria, leukocyturia without hypercalciuria, and a negative urine culture." (PMID 37108489, 2023). "A complete calcium and PTH dataset were available in 149 participants that included 17 of the 25 participants with hypercalcemia." (PMID 37293490, 2023). "In PHPT, the PTH level is usually elevated or inappropriately normal despite the presence of hypercalcemia." (PMID 37510130, 2023). "Hypervitaminosis D was suspected, and investigations were sent which showed raised serum creatinine, hypercalcemia, high serum vit D (25 OH) level, normal phosphate, and low parathyroid hormone level." (PMID 37415587, 2023). "Further workup revealed elevated parathyroid hormone levels and hypercalcemia, leading to a diagnosis of hyperparathyroidism." (PMID 39239219, 2023). "PHPT is an endocrine disorder characterized by an inappropriate excessive production of PTH that results in hypercalcemia." (PMID 36902844, 2023). "Nevertheless, there have been documented cases of hypercalcemia in patients receiving ICIs, although it appears to be non-PTH-mediated." (PMID 37779728, 2023). "Generally, PTH levels are used to distinguish hypercalcemia due to malignancy (physiologically suppressed) from that due to primary hyperparathyroidism (pathologically raised)." (PMID 37251673, 2023). "When compared to PTH, PTHrP triggers a similar osteoanabolic action but has a milder pro-resorptive effect and a lower tendency to induce hypercalcemia." (PMID 38117357, 2023). "Following intravenous saline hydration, zoledronic acid or denosumab is the standard treatment for PTH-independent hypercalcemia." (PMID 37328745, 2023). "Primary hyperparathyroidism (PHPT) is a common endocrine disorder characterized by excessive PTH secretion from one or more parathyroid glands, with resulting high PTH levels accompanied by hypercalcemia." (PMID 37841984, 2023). "Biochemical results usually show hypercalcemia and elevated PTH levels, although patients can be normocalcaemic." (PMID 36563301, 2023). "The patient is a 67-year-old female with a history of recurrent nephrolithiasis who presented with hypercalcemia, elevated PTH level, and hypocalciuria." (PMID 38021951, 2023). "Some patients require treatment because they have autonomy parathyroid tissue, hypercalcemia, high PTH, and cardiovascular and bone mineral metabolism disorders." (PMID 37069889, 2023). "Hypercalcemia workup showed suppressed parathyroid hormone (PTH), normal PTHrP, and high 1,25-dihydroxyvitamin D (1,25(OH)2D) serum levels." (PMID 36751194, 2023).